COL9A2 (collagen type IX alpha 2 chain)
Description:
Structural component of hyaline cartilage and vitreous of the eye.
Synonyms: MED; DJ39G22.4; EDM2; STL5
Tractability: Antibody: its Gene Ontology location is reachable by antibodies, with high confidence; UniProt places it where antibodies can reach, with medium confidence; UniProt predicts a signal peptide or a membrane-spanning region.
Gene: Protein-coding gene on chromosome 1 (40,300,487 to 40,317,813, reverse strand). Ensembl gene ENSG00000049089.
Subcellular location: Secreted, extracellular space, extracellular matrix
Subcellular location (Human Protein Atlas): Vesicles; Predicted to be secreted
Pathways (Reactome):
Extracellular matrix organization: Assembly of collagen fibrils and other multimeric structures; Collagen biosynthesis and modifying enzymes; Collagen chain trimerization; Collagen degradation; ECM proteoglycans; Integrin cell surface interactions
Developmental Biology: NCAM1 interactions
Signal Transduction: Signaling by PDGF
Gene Ontology:
Molecular function: protein binding; protein homodimerization activity; extracellular matrix structural constituent conferring tensile strength
Biological process: extracellular matrix organization; skeletal system development
Cellular component: collagen type IX trimer; extracellular matrix; endoplasmic reticulum lumen; extracellular region
Genetic constraint (gnomAD): Loss-of-function variants: 64 observed, 96.43 expected, observed/expected ratio (o/e) 0.66, 90% interval 0.54 to 0.82. The upper end of that interval is the gene's LOEUF score, 0.82, which puts it in group 3 of 6, group 1 being the genes least tolerant of losing a copy. Missense variants: 881 observed, 893.72 expected, observed/expected ratio (o/e) 0.99, 90% interval 0.93 to 1.04. Synonymous variants: 353 observed, 328.99 expected, observed/expected ratio (o/e) 1.07, 90% interval 0.98 to 1.17.
Gene-disease validity (ClinGen):
ClinGen rates the evidence that COL9A2 causes each of these diseases.
Stickler syndrome (autosomal recessive): Limited. Stickler syndrome is an inherited vitreoretinopathy characterized by the association of ocular signs with more or less complete forms of Pierre-Robin sequence, bone disorders, and sensorineural deafness (10% of cases).
Homologues: Orthologues: chimpanzee COL9A2 (99% identical), macaque COL9A2 (96% identical), mouse Col9a2 (91% identical), dog COL9A2 (91% identical), rat Col9a2 (90% identical), tropical clawed frog col9a2 (73% identical), rabbit COL9A2 (71% identical), zebrafish col9a2 (68% identical). Paralogues in human: COL11A1 (45% identical), COL5A1 (44% identical), COL24A1 (44% identical), COL11A2 (43% identical), COL5A3 (42% identical), COL27A1 (41% identical), COL4A5 (39% identical), COL4A1 (39% identical), COL2A1 (39% identical), COL4A4 (38% identical), COL7A1 (38% identical), COL3A1 (37% identical), and 25 more.